NOTCH3 (notch receptor 3)
Diseases named in the same sentence as NOTCH3 in open-access papers (continued):
Sharing a sentence is not in itself a finding about the gene and the disease.
CADASIL (continued). "Mutations in NOTCH3 may cause cerebral autosomal dominant arteriopathy with subcortical infarcts and leukoecephelopathy (CADASIL), a syndrome characterized by systemic vascular smooth muscle cell (VSMC) degeneration." (PMID 18987747, 2008). "NOTCH3 mutations have been identified as a genetic cause of CADASIL." (PMID 17996090, 2007). "Moreover, we further demonstrated that NOTCH3 mutations cause anomalies of the large intracranial arteries, coronary artery disease, and metabolic abnormalities through a pathogenesis similar to that of classical CADASIL." (PMID 41018180, 2025). "In addition to this, patients with a homozygous NOTCH3 mutation also seem to exhibit a clinical phenotype belonging to the classical clinical spectrum of CADASIL, whereas some reports have emphasized an increased disease severity in homozygous carriers, the exact mechanism of which is still unclear." (PMID 41018180, 2025). "Vascular NOTCH3 protein ectodomain aggregation is a pathological hallmark of cerebral autosomal dominant arteriopathy with subcortical infarcts and leukoencephalopathy (CADASIL), a monogenic small vessel disease typically caused by cysteine‐altering variants in NOTCH3." (PMID 40265482, 2025). "Also, one study evaluating patients with cerebral autosomal dominant arteriopathy with subcortical infarcts and leukoencephalopathy (CADASIL), a NOTCH3 mutation-related SVD, reported that similar small-vessel alterations can be found on myocardial specimens and in the brain." (PMID 37926793, 2023). "NOTCH3 is known to be associated with fatal dominant inherited disorders such as myofibromatosis, cerebral arteriopathy with subcortical infarcts and leukoencephalopathy (CADASIL) and lateral meningocele syndrome (OMIM # 600276), as well as different forms of cancer." (PMID 35361830, 2022). "NOTCH3 is critical for the function of mural vascular cells and pathogenic variants of NOTCH3 associated with mutations in the extracellular domain of NOTCH3 cause cerebral autosomal dominant arteriopathy with subcortical infarcts and leukoencephalopathy (CADASIL)." (PMID 35536858, 2022). "Interestingly, NOTCH3 mutations are responsible for CADASIL (Cerebral Autosomal Dominant Arteriopathy with Subcortical Infarcts and Leukoencephalopathy), the most common genetic cause of small vessel disease ischemic stroke, often associated with migraine with aura." (PMID 34946902, 2021). "Furthermore, the NOTCH3 p.R75P mutation may be underdiagnosed in early-onset lacunar infarctions due to the atypical clinical and neuroimaging features of CADASIL." (PMID 32477100, 2020). "The expression of NOTCH3 is ubiquitous in adults; however, due to mutations associated with cerebral autosomal dominant arteriopathy with subcortical infarcts and leukoencephalopathy (CADASIL), some studies suggest that NOTCH3 also plays a role in maintaining vascular homeostasis." (PMID 31915071, 2020). "Hence, NGS has increased our capabilities to identify NOTCH3 mutations causative of CADASIL, although the increased variety and relatively low diagnostic yield highlight that there may be other genes or mechanisms which contribute to or cause CADASIL." (PMID 31915071, 2020). "Cys-sparing mutations are contradictory to the hypothesis that Cys-changing mutations in NOTCH3 are responsible for the disease mechanism in CADASIL; however, multiple case studies have identified Cys-sparing mutations in NOTCH3 (p.R61W, p.R75P, p.R213K, p.A1020P and p.T1098S) as a cause of CADASIL." (PMID 31915071, 2020). "Similarly, the mutation c.445G>T (p.G149C) was reported in 5 individuals with CADASIL, which supported our hypothesis that the institution of glycine at position 149 of NOTCH3 is a potential pathogenic cause of CADASIL." (PMID 25098330, 2014).
CADASIL (continued). "The process depends on acidic pH and a reducing environment, and the enrichment of cleavage products N-terminal NOTCH3 fragments (NTF) in GOM within the media of cerebral arteries of CADASIL patients was confirmed using specific antibodies." (PMID 40470487, 2025). "Two key pathophysiological mechanisms are so far thought to contribute to the emergence and progression of CADASIL: aberrant NOTCH3 aggregation and aberrant NOTCH3 signaling." (PMID 41018180, 2025). "The accumulation of granular osmiophilic material (GOM), which contains the NOTCH3 extracellular domain (NOTCH3ECD), is detected via skin biopsies and is considered a hallmark pathological feature of CADASIL." (PMID 41018180, 2025). "CADASIL is a progressive disorder with an onset during middle age and is characterised by accumulation of the NOTCH3 Extracellular domain (ECD), which comprises of 34 tandem Epidermal Growth Factor (EGF)-modules." (PMID 40764588, 2025). "The accumulation and deposition of NOTCH3 ECD within the walls of small blood vessels are crucial pathological hallmarks of CADASIL." (PMID 39201482, 2024). "Cerebral autosomal dominant arteriopathy with subcortical infarcts and leukoencephalopathy (CADASIL) is a genetic vascular dementia characterized by age-related degeneration of vascular mural cells and accumulation of a NOTCH3 mutant protein." (PMID 39303912, 2024). "The alteration of NOTCH3 was observed in patients with inherited cerebral autosomal-dominant arteriopathy disease with subcortical infarct and leukoencephalopathy syndrome (CADASIL), characterized by cerebral developments dysfunction." (PMID 39273632, 2024). "NOTCH3 haploinsufficiency alone is insufficient to produce CADASIL symptoms, as demonstrated by the mainly asymptomatic carriers of LoF variants in the families described here, consistent with similar observations in previously published reports." (PMID 39191170, 2024). "The most severe NOTCH3-associated SVD phenotype is also known as cerebral autosomal dominant arteriopathy with subcortical infarcts and leukoencephalopathy (CADASIL)." (PMID 38713890, 2024). "Here, we performed an extended immunohistological screen to identify proteins that localize with NOTCH3 in the pathological media of CADASIL." (PMID 36753487, 2023). "We also analyzed and summarized the genetic spectrum of NOTCH3 and clinical features of CADASIL patients in different populations." (PMID 35822697, 2022). "In patients with CADASIL, accumulation and aggregation of Notch3 ECD have been shown to be the main component of the pathological structure GOM surrounding the VSMCs in small arteries and capillaries, which eventually degenerate." (PMID 35223989, 2022). "It is noteworthy that the plasma level of NOTCH3 ECD (N3ECD) was lower significantly in transgenic mouse models of CADASIL than in the control mice." (PMID 36142458, 2022). "Brain MRI findings reportedly varied considerably between patients with CADASIL and were dependent on the NOTCH3 genotype." (PMID 35775048, 2022). "Patients with CADASIL were found to have SQSTM1 gene mutations, with the damaged NOTCH3 and p62 genes encoding key proteins in the autophagic lysosomal pathway." (PMID 36139821, 2022). "Cerebral autosomal dominant arteriopathy with subcortical infarcts and leukoencephalopathy (CADASIL), the most common hereditary cerebral small vessel disease (CSVD), is caused by pathogenic mutations in NOTCH3 located on chromosome 19p13." (PMID 36570541, 2022). "The genetic spectrum of NOTCH3 and clinical features of CADASIL patients were analyzed and summarized in different populations." (PMID 35822697, 2022). "Typically, rare variants within NOTCH3 are associated with a monogenic subtype of CVD called cerebral autosomal dominant arteriopathy with subcortical infarcts and leukoencephalopathy (CADASIL)." (PMID 34584092, 2021).
CADASIL (continued). "Cerebral autosomal dominant arteriopathy with subcortical infarcts and leukoencephalopathy (CADASIL, OMIM NO.125310) is a cerebral small vessel disease caused by mutations in the NOTCH3 gene." (PMID 34335700, 2021). "Missense mutations in cysteine residues within any of the 34 EGF domains of the NOTCH3 gene have been identified in the majority of Cerebral Autosomal Dominant Arteriopathy with Subcortical Infarcts and Leukoencephalopathy (CADASIL) patients." (PMID 34200313, 2021). "Cerebral autosomal dominant arteriopathy with subcortical infarcts and leukoencephalopathy (CADASIL) is the most common hereditary form of cerebral small vessel disease (SVD) and caused by mutations in the NOTCH3 gene." (PMID 33898742, 2021). "However, recent data suggest a higher prevalence of NOTCH3 pathogenic variants in the general population worldwide, with the highest frequency in Asiatic descendant, suggesting that CADASIL may manifest with milder clinical variants that currently remain undiagnosed." (PMID 32231578, 2020). "Our findings identify a Notch3-regulated pathway involving interplay between the ER stress response and Rho kinase in the vasculopathy of CADASIL." (PMID 31647781, 2019). "Investigation of the resulting molecular conformations of the mutants shed light to the structural properties of the Notch3 3D organisation which lead to the activation or deactivation of the Notch3 protein and eventually to CADASIL disease." (PMID 31218211, 2019). "It is caused by mutations in the NOTCH3 gene which lead to the characteristic and early accumulation of the NOTCH3 extracellular domain (Notch3ECD) around smooth muscle cells and pericytes in patients and mice with CADASIL." (PMID 31753008, 2019). "Even though CADASIL is a rare disease, its linkage to NOTCH3 makes it very interesting from a basic research point of view." (PMID 31218211, 2019). "A diagnosis of CADASIL requires the identification of genetic changes in the NOTCH3 gene, which is located on chromosome 19." (PMID 31146726, 2019). "Background and objectives: NOTCH3 gene variations play a significant role in cerebral autosomal dominant arteriopathy with subcortical infarcts and leukoencephalopathy (CADASIL)." (PMID 31288479, 2019). "Neomorphic heterozygous mutations in NOTCH3, one of the four human NOTCH receptors, cause cerebral autosomal dominant arteriopathy with subcortical infarcts and leukoencephalopathy (CADASIL)." (PMID 25870235, 2015). "Mice mutant for Notch1 and Notch3 develop arteriovenous malformations and display hallmarks of the ischemic stroke disease CADASIL." (PMID 26563570, 2015). "Cerebral autosomal dominant arteriopathy with subcortical infarcts and leukoencephalopathy (CADASIL) is identified by aggregates of NOTCH3 extracellular domain (N3ECD) along capillaries and the deposition of granular osmiophilic material (GOM)." (PMID 25303037, 2015). "The accumulation and deposition of Notch3-ECD, an early manifestation and hallmark of CADASIL, is considered the starting point of a chain of pathological events eventually causing brain vessel dysfunction." (PMID 25190493, 2014). "Although these exons are not classically associated with CADASIL, variants within this region have been reported in individuals with a clinical CADASIL phenotype and may be impact the structural stability of the NOTCH3 homodimer." (PMID 41300806, 2025). "The combined presence of both NOTCH3 and RNF213 variants may lead to a diagnosis of CADASIL due to an accelerated clinical course or a mixed phenotype." (PMID 40869930, 2025). "CADASIL is an autosomal dominant inherited vasculopathy and is the most common single‐gene disorder causing stroke, with more than 200 different NOTCH3 p.R544C mutations in patients worldwide, indicating that CADASIL has considerable genetic heterogeneity." (PMID 38935968, 2024). "The pathological mechanism of CADASIL remains elusive, and there is no consensus on how NOTCH3 mutations lead to the occurrence of CADASIL." (PMID 39176342, 2024).
CADASIL (continued). "Aggregation of NOTCH3 extracellular domain (ECD) in pericytes is implicated in the etiology of cerebral autosomal dominant arteriopathy with subcortical infarcts and leukoencephalopathy (CADASIL)." (PMID 38769116, 2024). "It had been reported that NOTCH3 involved in cardiac development, was related to cerebral autosomal dominant arteriopathy with subcortical infarcts and leukoencephalopathy (CADASIL) that might share genetic pathways with PFO." (PMID 39872005, 2024). "We propose that the MCT sign observed in NOTCH3 R75P-related CADASIL patients may serve as a potentially characteristic imaging feature." (PMID 37681004, 2023). "Our data provide proof‐of‐principle that an active immunization strategy can reduce NOTCH3 aggregation in a pre‐clinical model of CADASIL and thus may be beneficial also in the treatment of CADASIL." (PMID 36524456, 2023). "CADASIL (Cerebral Autosomal Dominant Arteriopathy with Subcortical Infarcts and Leukoencephalopathy) is a genetic small vessel disease (SVD) caused by heterozygous variants in the NOTCH3 gene." (PMID 37361999, 2023). "CADASIL (cerebral autosomal dominant arteriopathy with subcortical infarcts and leukoencephalopathy) is the most common familial form of stroke, which is caused by mutations located in the epidermal growth factor (EGF)-like repeats of the NOTCH3 gene." (PMID 35223989, 2022). "Despite widespread deposits of mutant NOTCH3 protein in small arteries and capillaries, the clinical manifestations of CADASIL are only related to the central nerve system, in the form of migraine, acute encephalopathy, lacunar infarcts, cognitive impairment, gait, and mood disturbances." (PMID 34415564, 2022). "Notch3 is a gene involved in the pathogenesis of CADASIL, though it is currently not known if the mutations in Notch3 are causative." (PMID 36440263, 2022). "In this regard, it was recently shown that a mutation in NOTCH3 causes cerebral autosomal‐dominant arteriopathy with subcortical infarcts and leukoencephalopathy (CADASIL), and NOTCH3 selective agonists were suggested to be potentially effective in treating the disease." (PMID 34042293, 2021). "The pedigree had no phenotypic manifestations of either SCA37 or CADASIL, although the proband had both phenotypes, suggesting NOTCH3 gene mutations not only cause CADASIL, but also play an important role in the progression of SCA37." (PMID 34222332, 2021). "CADASIL (cerebral autosomal dominant arteriopathy with subcortical infarcts and leukoencephalopathy, OMIM#125310) is an autosomal dominant inherited small vessel disease (SVD) caused by mutations in the NOTCH3 gene (19p13)." (PMID 33767277, 2021). "Over 200 Notch3 mutations have been found to be associated with CADASIL, but it should be noted that we currently do not know if loss of function mutations are causative as well." (PMID 33800271, 2021). "Although insightful in understanding the pathology, mouse models with Notch3 mutations or deletions do not fully recapitulate the clinical features of CADASIL." (PMID 34200313, 2021). "However, sequencing of NOTCH3 is now used as a diagnostic tool with studies finding congruence between NOTCH3 mutations and GOM in the diagnosis of CADASIL." (PMID 31915071, 2020). "Pericytes express Notch3 and are first affected by Notch3 aggregation in Notch3R169C mice, suggesting pericytes might be a main contributor in the pathogenesis of CADASIL." (PMID 32317958, 2020). "Accumulation and deposition of Notch3 extracellular domain within vessel walls is a key pathological feature in CADASIL patients and is believed to be responsible for the formation of granular osmiophilic material (GOM) on the surface of vascular smooth muscle cells and pericytes." (PMID 31218211, 2019).
CADASIL (continued). "Cerebral autosomal dominant arteriopathy with subcortical infarcts and leukoencephalopathy (CADASIL) is the most frequent monogenic form of SVD and is caused by mutations in the NOTCH3 gene 135, leading to NOTCH3 protein accumulation, white matter lesions (WML), and subcortical infarcts." (PMID 31617312, 2019). "We found that SVCI patients, regardless of the presence of NOTCH3 variants, showed significantly more microstructural alterations and cortical thinning than typical CADASIL patients." (PMID 30692550, 2019). "In this instance, the use of SS may still miss mutations in a proportion of patients suggesting that screening of all coding regions in NOTCH3 is of benefit for the comprehensive molecular diagnosis of CADASIL." (PMID 27881154, 2016). "Traditionally, it is believed that the pathological changes of CADASIL are due to the mutations of NOTCH3 gene, and the development of the CADASIL is not related to other vascular disease such as atherosclerosis." (PMID 27206574, 2016). "Also, NOTCH3 accumulation is a plausible surrogate marker for CADASIL because it is universally present in the cerebrovasculature of CADASIL patients and is believed to play an important role in disease pathophysiology." (PMID 26715087, 2015). "Although arteriopathies in the tail and, when challenged, cortical vessels have been observed in knockout mice, important pathologies and hallmarks of CADASIL – including Notch3 ectodomain deposits, leukoencephalopathy and lacunar infarcts – have not been found." (PMID 23720232, 2013). "Analysis of Notch3 mutations, consistent with cerebral autosomal dominant arteriopathy with subcortical infarcts and leukoencephalopathy (CADASIL), was negative." (PMID 23393592, 2013). "This possibility provides a framework to identify additional proteins that could interact with NOTCH3 in the pathogenesis of CADASIL." (PMID 23028706, 2012). "Cerebral Autosomal Dominant Arteriopathy with Subcortical Infarcts andLeukoencephalopathy (CADASIL) é uma arteriopatia cerebralhereditária causada por mutações no gene Notch-3." (PMID 29213795, 2012). "NOTCH3 mutations may no longer be simply a disease of the small blood vessels of the brain-typical of CADASIL-but a new spectrum of diseases that share the same pathogenesis as NOTCH3 mutations." (PMID 41018180, 2025). "Furthermore, germline mutations in NOTCH3 affecting the number of cysteines in its extracellular domain (ECD) cause Cerebral Autosomal Dominant Arteriopathy with Subcortical Infarcts and Leukoencephalopathy (CADASIL)." (PMID 39537978, 2025). "Provocatively, germline NOTCH3 ECD mutations perturbing cysteine numbers cause Cerebral Autosomal Dominant Arteriopathy with Subcortical Infarcts and Leukoencephalopathy (CADASIL), a type of vascular dementia, suggesting an unexpected link between CADASIL and CH." (PMID 39537978, 2025). "Given the fact that CADASIL is a progressive disorder and it has been shown that the cerebrovascular NOTCH3 score increases with age in CADASIL mouse models, we had expected to find an association between the NOTCH3 score and age, which was not the case." (PMID 40265482, 2025). "In this case series study of 43 patients with suspected CADASIL, we detected vascular Notch3 ECD deposits in all 10 patients by immunohistochemical staining using unfixed frozen biopsied samples, which were confirmed to have pathogenic NOTCH3 variants causing CADASIL." (PMID 35775048, 2022). "The pathological relevance of this phenomenon is underscored by the finding that NOTCH3 mutations cause the most commonly inherited cerebral small vessel disease (SVD), cerebral autosomal dominant arteriopathy with subcortical infarcts and leukoencephalopathy (CADASIL)." (PMID 35409031, 2022).